CRP (C-reactive protein)
Diseases named in the same sentence as CRP in open-access papers (continued):
Sharing a sentence is not in itself a finding about the gene and the disease.
atrial fibrillation (continued). "Several studies have reported a higher serum CRP level in patients with atrial fibrillation in comparison to control subjects in sinus rhythm." (PMID 33335617, 2020). "Higher CRP levels were associated with younger age, higher BMI, COPD, atrial fibrillation, RV dysfunction, reduced exercise tolerance, higher circulating levels of ET-1, aldosterone, and NT-pro BNP." (PMID 33117832, 2020). "A clinical trial including 80 patients showed that CRP lowering with atorvastatin appeared to be effective in eliminating paroxysmal atrial fibrillation in daily life." (PMID 32587865, 2020). "The concentration of CA125 was positively related to age, hospitalization for HF and history of atrial fibrillation and chronic obstructive pulmonary disease, levels of NT-proBNP, IL-6, hs-CRP and triglycerides." (PMID 31058877, 2019). "They examined 40 patients after CABG and revealed that postoperative elevated C-reactive protein and resistin serum levels were significantly higher in patients with postoperative atrial fibrillation." (PMID 31842758, 2019). "Sensitivity andspecificity for C-reactive protein with a cut-off value of 12 mg/dL on the15th postoperative day were 83.3% and 88.9%, respectively.The effect of body mass index on atrial fibrillation recurrence was 3.2times." (PMID 30652742, 2018). "Estimated-GFR and atrial fibrillation showed the better relation with NT-proBNP, followed by polypharmacy, CRP, albumin and age." (PMID 27077910, 2016). "Patients with atrial fibrillation demonstrate evidence of inflammation, with elevated levels of inflammatory markers, including C-reactive protein, interleukin-6, and tumor necrosis factor-α." (PMID 21896397, 2012). "Markers of cardiovascular (atrial fibrillation), renal (creatinine, urea), immune-inflammatory (IL-6, CRP, ESR, procalcitonin, presepsin), metabolic (FBG), hepatic (AST, ALT), and comorbidity burden (CCI) domains were analyzed using logistic and LASSO regression with bootstrap validation." (PMID 42279490, 2026). "For atrial fibrillation, obese patients again exhibited significantly higher NT-proBNP (7400 ± 2600 pg/mL vs. 4500 ± 2100 pg/mL, p < 0.001), Troponin I (125 ± 330 ng/mL vs. 95 ± 300 ng/mL, p = 0.01), and inflammatory markers like CRP, CK-MB, and D-dimer." (PMID 40002762, 2025). "Our study provides preliminary evidence that postoperative CRP levels at 48 hours and NLR at 24 hours could serve as potential markers for identifying patients at increased risk of postoperative atrial fibrillation following cardiac surgery." (PMID 40599146, 2025). "We next analyzed the same parameters according to the type of procedure that was performed, combining MitraClip and LAAC patients into a combined cohort based on similar clinical characteristics (high presence of atrial fibrillation, NTproBNP, CRP, and CHA2DS2-VASc score)." (PMID 38922424, 2025). "Elevated CRP levels around the time of surgery may contribute to atrial fibrillation (AF) development." (PMID 40599146, 2025). "In patients with atrial fibrillation, preoperative uric acid, B-type natriuretic peptide, hypersensitivity C-reactive protein, erythrocyte sedimentation rate, and left atrial diameter are risk factors for atrial fibrillation or atrial flutter recurrence after radiofrequency ablation." (PMID 38750504, 2024). "The authors concluded that elevated plasma CRP alone does not increase the risk of atrial fibrillation." (PMID 38541078, 2024). "In addition, significant differences were observed in several other variables during the univariate analysis, including WBC count, NLR, CRP, BMI, history of atrial fibrillation, consciousness level, and tracheotomy." (PMID 38730021, 2024). "Correlations between CRP level, leukocytes and the occurrenceof postoperative atrial fibrillation." (PMID 39077087, 2023).
atrial fibrillation (continued). "Multivariate logistic regression analysis showed elevated pre-operative and postoperative first-, thirdand seventh-day red blood cell distribution volume, erythrocyte sedimentation rate and C-reactive protein as independent predictors of early postoperative atrial fibrillation." (PMID 36637452, 2023). "Since it has been shown that atrial flutter and atrial fibrillation both coincide with higher CRP levels, this may be a reason for higher baseline CRP levels in the digoxin group on d1." (PMID 35407370, 2022). "Besides, these studies have investigated the inflammatory pathway of atrial fibrillation patients only by determine CRP plasma levels, and in recent years numerous evidence suggest to avoid the use of the historical term “lone AF”." (PMID 32364529, 2020). "It has been hypothesized that CRP may attach to the atrial myocyte and initiate a complement‐mediated local inflammation contributing to the pathophysiology of atrial fibrillation." (PMID 33335617, 2020). "Additionally, pericardial and epicardial fat have increased markers of inflammation including C-reactive protein, IL-6, IL-1β, and TNF-α, which are associated with increased incidence, severity and reoccurrence of atrial fibrillation." (PMID 30534081, 2018). "D-dimer and vWF were significantly and positively associated with NT-proBNP (a marker of neurohormonal activation and left ventricular wall stress) even after adjustment for age, lifestyle characteristics, renal dysfunction, atrial fibrillation (AF) and inflammation (C-reactive protein)." (PMID 28043678, 2017). "Whether depressive symptom dimensions in atrial fibrillation individuals are mediated through elevated inflammatory activity was assessed by CRP measurement." (PMID 24324579, 2013). "Recently, the involvement of inflammation in atrial fibrillation has been documented, and high levels of pro-inflammatory proteins, such as C-reactive protein, have been suggested to promote the persistence of atrial fibrillation by inducing structural and/or electrical remodelling of the atria." (PMID 22614666, 2012). "It has been shown on large general population cohorts of 47,000 individuals that systemic inflammation, estimated by CRP, increases the risk of developing atrial fibrillation independently of other risk factors, but not in subjects with elevated CRP levels due to genetic causes." (PMID 38672728, 2024). "Furthermore, CRP might be useful as an independent factor to predict the recurrence of atrial fibrillation." (PMID 37443830, 2023). "Furthermore, previous studies have shown associations between CRP and cytokines such as IL-6 and atrial fibrillation and other arrhythmias in the absence of CAD, raising the possibility of a direct electrophysiological effect." (PMID 31234795, 2019). "A variety of studies have also implicated inflammation in having an aetiological role in the initiation and perpetuation of atrial fibrillation due to evidence of raised inflammatory markers such as interleukin-6 and C-reactive protein in AF patients." (PMID 23401843, 2013). "Anti-inflammatory agents may decrease the C-reactive protein and ameliorate atrial fibrillation." (PMID 20084192, 2010). "Furthermore, systemic inflammation may actually trigger cardiac arrhythmia as evidenced by the finding that elevated serum CRP was predictive of the recurrence rate of atrial fibrillation, another type of cardiac arrhythmia." (PMID 19479011, 2009). "A novel clinical score integrating low‐voltage zone extent (LVZ), high‐sensitivity C‐reactive protein (hs‐CRP), red cell distribution width (RDW), and left atrial diameter (LAD) predicts atrial fibrillation recurrence post‐ablation." (PMID 41223074, 2025). "Baseline data analysis revealed that several key indicators, including DBP, atrial fibrillation incidents, NIHSS score, d-D, hs-CRP, NLR, SIRI, SII, NT-proBNP, as well as the S100-β, were significantly elevated in the POCD group compared to the non-POCD group." (PMID 39711844, 2024).
atrial fibrillation (continued). "Elevated levels of inflammatory markers, such as C-reactive protein (CRP), common in IBD, can exacerbate atrial fibrillation, contributing to a more complicated disease course." (PMID 39105025, 2024). "The patients differed in terms of age, length of education, frequency of atrial fibrillation, CIRS, neglect and vision deficits in hospital, pre-hospital mRS and CRP level." (PMID 36803740, 2023). "In present study, we found CRP and SIRI were significant predictors of preoperative atrial fibrillation, that was to say inflammation was likely related to the genesis of preoperative atrial fibrillation." (PMID 37202743, 2023). "In our study, we present a simple risk score for prediction of the primary endpoint, which encompasses older age, presence of atrial fibrillation at baseline ECG, lower baseline systolic blood pressures and higher C-reactive protein and potassium levels." (PMID 34501427, 2021). "Age (OR 1.1, CI: (0.66–1.86)), atrial fibrillation (AF) on baseline-ECG (OR 3.4, CI: (1.74–6.8)), systolic blood-pressure (OR 0.7, CI: (0.53–0.96)), potassium (OR 1.3, CI: (0.99–1.73)) and C-reactive-protein (1.4, CI (1.04–1.76)) were associated with CV-events." (PMID 34501427, 2021). "Regression analysis investigated the relationship between Hs-CRP level and severity of OSA, and further assessed the factors influencing postoperative atrial fibrillation, duration of hospitalization, and hospital cost." (PMID 34332541, 2021). "Others included were age, NYHA functional class, atrial fibrillation, LVEF, IVS, log BNP, dFLC and CRP." (PMID 31189919, 2019). "For example, post-operative atrial fibrillation (the most common major complication of CABG) has a well-defined positive correlation with IL-6 and CRP levels post-operatively." (PMID 30453474, 2018). "Patients with unfavorable discharge outcomes were generally older, more likely to have atrial fibrillation, and more likely to have higher NIHSS and serum CRP on admission." (PMID 27096104, 2016). "In a study of 106 outpatients with atrial fibrillation (AF), it was reported that AF patients have higher levels of IL-6, CRP, TF, and plasma viscosity compared with controls, and significant correlations were reported between these inflammatory markers (IL-6, CRP) and prothrombotic plasma markers." (PMID 19936194, 2008). "Therefore, alongside CRP and NLR, preoperative IL-17A can be considered a potentially significant marker for atrial fibrillation following cardiac surgery." (PMID 40599146, 2025). "Univariate and multivariate Cox regression analyses showed that preoperative UA, BNP, high-sensitivity CRP, ESR, LAD, MVG, and LAMD were significantly associated with radiofrequency ablation in patients with non-isolated atrial fibrillation." (PMID 38750504, 2024). "Risk factors for sudden death in patients undergoing hemodialysis include male sex, advanced age, cardiovascular disease, atrial fibrillation, a higher cardiothoracic ratio (CTR), a higher C-reactive protein (CRP) level, predialytic hyperphosphatemia, and predialytic hyperkalemia." (PMID 38436900, 2024). "Therefore, UA, BNP, five indicators of high-sensitivity CRP, ESR, and LAD were used to establish a predictive model for postoperative atrial fibrillation recurrence." (PMID 38750504, 2024). "On further investigation, atrial fibrillation had normal ventricular response, lactate was 3.0, procalcitonin (PCT) was 162 ng/mL, C-reactive protein (CRP) was 60.8 mg/dL, and N-terminal pro-brain natriuretic peptide (NT-proBNP) was > 9000, with urea at 281 mg/dL and creatinine at 5.69 mg/dL." (PMID 37029429, 2023). "A single high-dose steroid therapy does not change the level of CRP and is not sufficient to prevent early postoperative recurrence of atrial fibrillation." (PMID 35707046, 2022).
atrial fibrillation (continued). "Among other clinical and laboratory variables, age, sex, current smoking, atrial fibrillation, previous MI, hemoglobin level, WBC count, hs-CRP level, homocysteine level, uric acid level, and initial NIHSS score were significantly associated with poor functional outcome at discharge." (PMID 34682842, 2021). "Additionally, CRP at 48h and ΔCRP showed significantly elevated mean levels in the atrial fibrillation group compared to those without, also reaching statistical significance (P < 0.05)." (PMID 40599146, 2025). "Interestingly, atrial fibrillation (AF) and COVID-19 infection appear to share some pathophysiological features, both being driven by an immune response, with inflammatory markers, such as C-reactive protein and cytokine interleukin (IL)-6, correlating with disease severity and mortality." (PMID 36755799, 2023). "For the patient subgroup without atrial fibrillation, the conditional effect was lowered and lost its significance on the 5% level (p = 0.06), which implies that the importance of CRP levels for clinical outcomes is predominantly seen in patients with atrial fibrillation." (PMID 37360331, 2023). "The present study showed CRP-induced activation and cross-talk of TLR4/NF-κB/TGF-β1 signaling pathway in a cardiomyocyte model, which may provide a potential target for future therapeutic interventions in inflammation-induced atrial fibrillation." (PMID 31391207, 2019). "This study aimed to reevaluate the prognostic role of CRP and determine the clinical impact of OSA severity on postoperative recovery, focusing on new-onset atrial fibrillation (AF), prolonged intubation time, and postoperative CPAP/AIRVO use as indicators of respiratory burden." (PMID 41153825, 2025). "Preoperative UA, BNP, high-sensitivity CRP, ESR, and LAD in patients with non-isolated atrial fibrillation were significantly correlated with the recurrence of atrial fibrillation after radiofrequency ablation." (PMID 38750504, 2024).
autoimmune disease (285 papers, 2004 to 2026). A disorder resulting from loss of function or tissue destruction of an organ or multiple organs, arising from humoral or cellular immune responses of the individual to their own tissue constituents. "High levels of CRP show that inflammation exists throughout the body and the high levels of CRP are associated with different diseases such as cardiovascular diseases autoimmune diseases and respiratory diseases." (PMID 40662069, 2025). "Acute infections with tissue damage, rheumatological diseases, autoimmune diseases, neurodegenerative disorders, malignancies, and similar tissue damage can cause a 10–100-fold increase in CRP levels (<1 mg/dL) within 6–72 h." (PMID 40282880, 2025). "Elevated CRP levels are associated with conditions such as bacterial infections, autoimmune diseases, and cardiovascular disorders, making CRP a valuable tool in clinical diagnostics and disease monitoring." (PMID 40507811, 2025). "Cortisol-mediated immunosuppression is compounded by stress-induced rises in IL-6, TNF-α, and C-reactive protein (CRP), producing low-grade systemic inflammation linked to cardiovascular, metabolic, and autoimmune diseases." (PMID 41196405, 2025). "Psoriasis (Ps) is another autoimmune disorder linked with increased C-reactive protein (CRP) in Ps patients." (PMID 38956704, 2024). "Women using hormonal contraceptives (HCs) exhibit numerous signs of chronic inflammation, including elevated C-reactive protein levels and greater risk of developing mood and autoimmune disorders." (PMID 37914104, 2024). "Indicated that GA, PROM (≥ 18 h) and maternal autoimmune diseases were independent risk factors for CRP ≥ 8 mg/L." (PMID 38302903, 2024). "TPOAb was associated with autoimmune diseases, and TPOAb titers correlate positively with high-sensitivity C-reactive protein levels." (PMID 38586463, 2024). "We also observed a putative causal effect of PTSD on autoimmune thyroid disease and CRP, consistent with epidemiologic evidence of stress- and trauma-related disorders predicting elevated systemic inflammation and onset of autoimmune disease." (PMID 38561342, 2024). "This meta-analysis provides first-time evidence that chronic elevation of CRP in autoimmune diseases is directly associated with an increased risk of later development of Alzheimer’s disease." (PMID 36776896, 2023). "Recently, several studies linked chronic CRP/mCRP systemic expression in autoimmune disease with increased risk of dementia and the mechanisms through which this occurs are investigated here." (PMID 37158450, 2023). "This analysis showed that serum albumin levels (P = 0.003), C-reactive protein concentrations (P = 0.012), and autoimmune diseases (P = 0.047) were associated with acute postoperative infection." (PMID 36684164, 2022). "An increase in serum levels of IL-6, tumor necrosis factor (TNF)-α, and C-reactive protein (CRP) can generally be observed in older adults and the susceptibility to infection and the prevalence of autoimmune disease converge." (PMID 35100595, 2022). "As for the univariate analysis, we found that patients with high preoperative CRP or who suffered from autoimmune diseases were associated with acute infection after primary TJA." (PMID 36684164, 2022). "Polygenic risk scores (PRS) of six autoimmune disorders, CRP, and 10 SMD-related mental phenotypes were calculated from GWAS." (PMID 35082268, 2022). "Hypermetabolism of the bone marrow or spleen has been associated with laboratory values such as C-reactive protein or hemoglobin and even prognosis in patients with several types of cancer and autoimmune disease." (PMID 33106925, 2021). "The diagnostic accuracies of fibrinogen and CRP were the same (77.78%) and outstanding compared to others in patients with combined autoimmune diseases." (PMID 34172035, 2021).